EPO (erythropoietin)
Diseases named in the same sentence as EPO in open-access papers (continued):
Sharing a sentence is not in itself a finding about the gene and the disease.
anemia (continued). "In patients with CKD anemia not requiring dialysis, Roxadustat elevates Hb levels in a dose-dependent manner, significantly decreases ferritin levels, and briefly increases endogenous EPO levels within or near the physiological range, compared to placebo at high doses." (PMID 41155680, 2025). "Moreover, combined PD and HD therapy has been shown to improve erythropoietin-resistant anemia, suggesting that dialysis efficiency, rather than modality alone, may be more critical for anemia management." (PMID 41157262, 2025). "Clinically, these patients were also more likely to receive erythropoietin, without any observed difference in bone marrow suppression, which likely implies the treatment intention was to timely improve red cell volume to avoid transfusion and/or the complications of anemia." (PMID 40003291, 2025). "Thus, while r-huEPO may prevent anemia, oral iron supplementation in conjunction with EPO may not be able to maintain adequate body iron stores and iron supply to the brain." (PMID 39599621, 2024). "However, by contrast with diabetic patients who may develop alloantibodies against insulin prior to exposure to the recombinant protein, the occurrence of anemia due to the production of alloantibodies against EPO has never been reported." (PMID 38672425, 2024). "Hence, anaemia and EPO would not be able to serve as early predictors of CKD." (PMID 39682316, 2024). "Previous studies found elevated serum erythropoietin levels in patients who presented with severe malaria-related anaemia in India, Kenya, Sudan and Thailand, but could not significantly correct the anaemia." (PMID 36989322, 2023). "Although anaemia has a significant negative impact on morbidity and mortality in renal dysfunction, it remained a particularly difficult challenge in this environment due to the very high cost of erythropoietin (EPO), which has necessitated higher blood transfusion rates with attendant consequences." (PMID 38784494, 2023). "Finally, we could not determine the etiology of anemia in these subjects due to the lack of measurement of serum levels of EPO, iron, vitamin B12 or folic acid." (PMID 35414128, 2022). "Suppressing the release of erythropoietin from kidney interstitial cells might benefit patients during erythrocyte transfusion at higher hemoglobin thresholds (e.g., 9–10 g/dL), even in the absence of clinical signs of anemia." (PMID 35054318, 2022). "However, excessive inflammation, malnutrition, and anemia are regarded as intervenient factors for the development of PICS, which may be treated using anti-inflammatory agents, nutrition therapy, exercise, or erythropoietin, thereby preventing PICS." (PMID 36233660, 2022). "Out of the 39 patients who received anemia treatment, approximately 71.8% (28/39) treated with iron therapy, folic acid, vitamin B12, and multivitamins, whereas 28.2% (11/39) underwent blood transfusion and none of the patients treated with erythropoietin-stimulating agents (ESAs)." (PMID 35464620, 2022). "DKD-related anemia developed earlier and was more severe than non-DKD-related anemia based on different mechanisms, such as source deficiency for RBC production, greater bleeding tendency, poor response to EPO, tubulointerstitial damage, chronic inflammation, etc.." (PMID 36614886, 2022). "In addition, there were only some placebo-controlled randomized controlled trials (RCTs) to investigate the efficacy of recombinant human erythropoietin in anemia profiles; none of these RCTs provided extra information about the multiple comparisons between different active treatments." (PMID 34436045, 2021). "Due to the increased serum erythropoietin levels but lack of distinct phenotype in steady-state TED, we hypothesized that the kinetics of Ypel4-deficiency might be accentuated in a situation of induced anemia." (PMID 34354145, 2021).
anemia (continued). "Therefore, no major difference in the hematologic responses to PHZ and EPO was observed in 1Mek1 and 1Mek2 mutants that could explain the anemia observed in these mutants." (PMID 34386488, 2021). "Thus, improvement of iron utilization in a CKD model using EPO and a HIF‐PHDi significantly reduced iFGF23, demonstrating that anemia is a primary driver of FGF23, and that management of iron utilization in patients with CKD may translate to modifiable outcomes in mineral metabolism." (PMID 32476270, 2020). "In several human studies, EPO production was defective or levels were not as high as would be expected for the degree of anemia observed, however, other studies reported elevated levels of EPO in the serum of African children with severe P. falciparum-related anemia." (PMID 32373101, 2020). "Because etiology of anemia in CRAS is multifactorial, this model may represent CHF patients who have higher EPO levels than expected from hemoglobin levels, who are known to have poorer prognosis than CHF patients who have lower EPO levels than expected from hemoglobin levels." (PMID 33328561, 2020). "However, systemic delivery of EPO, which is the current clinical practice for anemia, did not consistently show effectiveness and safety in clinical trials of patients with stroke, probably because of the poor BBB penetration of EPO, which leads to the requirement of a high, but toxic, dose of EPO." (PMID 30920178, 2019). "Interestingly, in iron-refractory iron deficiency anemia patients, as well as in Tmprss6-mutated mice, this downregulation of hepcidin by ERFE is not functional, and hepcidin transcription does not respond to administration of EPO." (PMID 29073189, 2017). "Due to the retrospective nature of our study we could not analyze anemia and its management in detail because different thresholds for ribavirin dose reduction, transfusion or use of erythropoietin were applied by different physicians, preventing statistical comparisons." (PMID 27388623, 2016). "The study end-point was 1) new anemia (<12.0 g/dl for women and <13.0 g/dl for men) for non-anemic patients, and 2) decreased hemoglobin levels greater than 1 g/dl and/or initiation of treatment including iron supplementation and EPO-stimulating agents for anemic patients." (PMID 25884723, 2015). "In addition, low or nonfunctional erythropoietin is accused of anemia." (PMID 22611373, 2012). "As CKD progresses, the interstitial cells transform into myofibroblasts that can no longer synthesize erythropoietin (EPO), resulting in anemia." (PMID 40620843, 2025). "Within this framework, erythropoietin (EPO) and its analogs have gained renewed interest not only in treating anemia but also in a variety of non-hematologic conditions, including neurodegeneration, metabolic dysfunctions, and ischemic injuries." (PMID 41012526, 2025). "Recombinant human EPO and erythropoiesis-stimulating agents can promote EPC differentiation and maturation to RBCs, and thereby effectively treat anemia; however, these agents do not prolong the survival of patients with cancer." (PMID 39474425, 2024). "Overall, HUS mice exposed to 20 ng/kg Stx develop anemia that transitions from hemolytic to non-hemolytic 21 days after HUS induction, without impaired EPO production, unchanged hepcidin or ferritin levels, but lowered mean corpuscular volume of erythrocytes." (PMID 39450175, 2024). "The use of HIF-PH inhibitors for anemia treatment in patients with both HF and CKD is rational due to their capacity to increase hemoglobin without high levels of EPO." (PMID 37374094, 2023). "EPO products, while reducing the need of PBT – especially in cancer-related or post radiation/chemotherapy anemia – have raised concerns due to the lack of a clear safety profile." (PMID 36691071, 2023). "When using erythropoietin stimulating agents (ESA), Hb corrections to normal values are not recommended, as complete correction of anaemia increases mortality." (PMID 35743505, 2022).
anemia (continued). "Nearly half of our patients 45 (45%) were not on erythropoietin (EPO) injections and were receiving blood transfusions for anaemia." (PMID 36705169, 2022). "EPO−/− and EPOR−/− mice die in utero at E13.5 due to lack of definitive erythropoiesis and the resultant severe anemia." (PMID 34603036, 2021). "Other than Socs1 and Socs3, Socs2, Spred1, Spred2, and Eaf1 were also found as EPO/EPOR target genes and negative-feedback components of EPO-induced erythropoiesis during anemia." (PMID 34281163, 2021). "Baseline anemia was also significantly associated with mortality (HR 2.40, 95% CI 1.51–3.80, p < 0.001), with Kaplan-Meier curves for anemia vs. non-anemia already diverging shortly after TAVR procedure, as opposed to EPO curves." (PMID 33330669, 2020). "Moreover, a study showed that Hb levels increased after treatment with an inhibitor of HIF-PH, while endogenous erythropoietin remained within the normal physiological range, which suggests that HIF-PHIs may use a mechanism different from ESAs to improve anemia." (PMID 33597868, 2020). "In conclusion, we found a large prevalence of anemia among CKD patients who were not given RRT, and the burden of patients who require treatment with erythropoietin is considerably large." (PMID 32240223, 2020). "In conclusion, low EPO levels, which are common even in anemic patients without CKD, predict rapid renal decline in type 2 diabetic patients with anemia." (PMID 31619722, 2019). "EPO treatment increased TFR2 protein both in C57BL/6 and mask mice, suggesting that the failure of EPO to correct the microcytic anemia in mask mice is not related to defective synthesis of this protein." (PMID 29073189, 2017). "Unlike mice that lack either EPO or EpoR resulting in death in utero, double knockout of both STAT5A and STAT5B is not embryonic lethal and, rather, results in fetal anemia and defective response in adult mice to erythroid stress." (PMID 24918289, 2014). "In Ohls’s study, treatment with oral and IV EPO was effective in preventing the decrease of Hb and HCT to the level of anemia of prematurity (<7 mg/dl) so that neither groups had a Hb less than 7 g/dL in the 4th week after birth." (PMID 22737576, 2012). "Collectively, these findings suggest that although baseline endogenous serum EPO concentration ≤ 200 U/L appears to be predictive of higher efficacy with ESA, luspatercept is a promising therapeutic option for the treatment of anemia in NTD patients with LR-MDS, regardless of serum EPO levels." (PMID 39572468, 2025). "A specific role for endogenous EPO in cardiovascular development was provided by mice lacking EPO or EPOR that exhibit developmental angiogenic and cardiac defects including ventricular hyperplasia prior to death in utero due to severe anemia." (PMID 38628440, 2024). "Our data show that intake of a phosphate-rich diet results in inflammation-induced hypoferremia and ineffective erythropoiesis leading to anemia through the actions of elevated FGF23 on erythroid progenitors, in the absence of hyperphosphatemia and despite increased EPO secretion." (PMID 39666728, 2024). "Roxadustat is a novel and oral hypoxia-inducible factor (HIF) prolyl hydroxylase inhibitor which raises endogenous erythropoietin concentrations by stabilizing HIF, and it has been recently endorsed for the treatment of anemia in patients with non-dialysis CKD." (PMID 36910473, 2023). "Hence, European Medicines Agency (EMA) approved EPO, but not DARBO, for the treatment of anemia due to MDS in patients with a sEPO < 200 U/L." (PMID 37504319, 2023). "As anemia appears not to be the sole driver of increased EPO levels during HUS and patients with pronounced kidney damage showed the lowest EPO levels, we next wanted to analyze the therapeutic potential of EPO and the non-hematopoietic EPO derivative pHBSP in a murine model of HUS." (PMID 36211426, 2022).
anemia (continued). "Consequently, iron supplementation, with or without the addition of erythropoietin, is the most commonly recommended therapeutical approach to CHF-mediated anaemia." (PMID 33467658, 2021). "Baseline HbA1c values may have been falsely lowered by anaemia accompanying CKD, although mean haemoglobin for the study cohort was 12.7 g/dL and no patients were treated with an erythropoietin-stimulating agent." (PMID 32908199, 2020). "This study suggested that under conditions of anemia, as opposed to mice with normal iron homeostasis, rescuing iron utilization during CKD may be a more potent suppressor of FGF23 than EPO and HIF-PHIs are stimulators." (PMID 32982979, 2020). "CKD patients with anemia were treated with erythropoietin (EPO)-stimulating agents (21.6%, p = 0.001) and supplemental iron therapy (36.3%, p = 0.001), and showed significantly lower ferritin levels (p < 0.001) than those without anemia." (PMID 30700016, 2019). "So, although EPO production might increase as a compensatory response to the anemia status, MR16-1 treatment improved anemia without decreasing EPO levels, and EPO is reported to decrease hepcidin expression levels." (PMID 27068103, 2016). "Actually, this response to the erythropoietic stimuli by exogenous recombinant human erythropoietin (rhEPO) further strengthens the hypothesis that the endogenous EPO, in spite of its higher plasmatic concentration, is not able to overcome anemia." (PMID 25867633, 2015). "Thus a simple model of molecular mimicry does not explain how anti-EPO autoantibodies would decrease following HAART and reverse anemia when the triggering anti-p17 antibodies remain unchanged." (PMID 26599070, 2015). "Improving renal anemia by erythropoietin could improve cognitive function, but one double-blind randomized trial of darbepoetin in CKD patients with moderate anemia did not specifically assess cognitive function." (PMID 25780391, 2015). "Rates of severe anaemia and fatigue were also somewhat lower than previously reported, although anaemia of any grade was more common in the CLD arm and transfusion rates were significantly higher in the CLD arm; information on erythropoietin use was not available." (PMID 20055981, 2010). "In this context, we could also not detect compensatory upregulation of PHD2 or PHD3 after HIF‐2 stabilization under anaemia or PHD inhibition, neither in medullary fibroblasts as a possible counterregulation to prevent EPO induction, nor in EPO+ and EPO− fibroblasts in the cortex." (PMID 40853869, 2025). "Other than a lack of EPO in CKD, other factors may contribute to anemia in patients with CKD." (PMID 36855344, 2023). "Targeted deletion in mice of either EPO or EpoR leads to a marked decrease in circulating primitive erythroblasts in utero by day E11.5, and definitive erythroid progenitor cells at the CFU-E (colony forming unit-erythroid) stage do not survive resulting in severe anemia and death at day E13.5." (PMID 22567318, 2012).
chronic kidney disease (441 papers, 2005 to 2026). Impairment of the renal function secondary to chronic kidney damage persisting for three or more months. "Simultaneously, chronic kidney disease's inability to produce adequate erythropoietin forms a vicious cycle, heightening the risk of acute heart failure." (PMID 38549043, 2024). "This study compares the cardiovascular risk in anemic chronic kidney disease patients treated with Roxadustat versus erythropoietin stimulating agents (ESAs)." (PMID 38962312, 2024). "Chronic kidney disease (CKD) often leads to renal anemia as a result of erythropoietin (EPO) deficiency and other factors such as shortened RBC (red blood cell) life range, iron deficiency and inflammation with higher hepcidin levels." (PMID 38338996, 2024). "The association of chronic kidney disease (CKD)—incorporating a decrease in erythropoietin levels—with this condition is defined as cardio-renal anemia syndrome (CRAS)." (PMID 36673114, 2023). "Recombinant human erythropoietin (rHuEPO) is prescribed to treat renal anemia associated with chronic renal failure and chemotherapy treatments." (PMID 35292912, 2022). "Hyporesponsiveness to erythropoietin stimulating agent (ESA) is associated with poor outcomes in patients with chronic kidney disease." (PMID 33863297, 2021). "Peginesatide is an erythropoietin analog for the treatment of anemia associated with chronic kidney disease (CKD)." (PMID 33996914, 2021). "The major complications associated with chronic kidney disease (CKD) include renal anemia caused by the insufficient production of the hematopoietic hormone erythropoietin (EPO) by the kidneys." (PMID 33656639, 2021). "The primary cause of renal anemia in chronic kidney disease (CKD) is the deficiency of endogenous erythropoietin mainly produced by kidneys." (PMID 34079677, 2021). "In chronic kidney disease ID is often caused by reduced hepcidin excretion by the kidneys, increased blood loss, and treatment with erythropoietin-stimulating agents." (PMID 33292849, 2020). "Recently, it has been associated with all-cause of mortality in geriatric patients diagnosed with chronic kidney disease, associated with higher C-reactive protein in patients with end-stage renal disease, and erythropoietin resistance." (PMID 31207869, 2019). "Chronic kidney disease (CKD) is characterized by renal anemia caused by a relative deficiency of endogenous erythropoietin secretion, increased blood loss, and shortened red blood cell survival." (PMID 30741616, 2018). "Potential risk factors for RLS including underlying cause of chronic renal failure, duration on dialysis, biochemical tests, dialysis adequacy, and erythropoietin and also venofer dosage in recent month and demographic data were also evaluated." (PMID 28497091, 2017). "PRCA caused by cross-reacting neutralizing antibodies against erythropoietin is a rare but known serious adverse event that has been observed with the use of erythropoietin in patients with chronic renal failure." (PMID 27733189, 2016). "Bone marrow senescence results in the decreased number of erythroblasts, which is partially related to the age-associated reduction of erythropoietin (EPO) production by the kidneys and to the high prevalence of chronic kidney disease in the elderly." (PMID 24453794, 2013). "However, high-dose EPO treatment in patients with chronic kidney disease was linked to an increased risk of serious cardiovascular events and mortality." (PMID 38628440, 2024). "In addition, among the transient receptor potential (TRP) channels, short transient receptor potential channel 5 (TRPC5) has been identified as a cause of erythropoietin-induced hypertension in patients with chronic kidney disease." (PMID 37125041, 2023). "Mechanistically, EPO-deficiency could be attributed to inflammatory or immune responses involving cytokine release, as well as primary or secondary chronic kidney disease in patients with cancer." (PMID 37208766, 2023).